CRP (C-reactive protein)
Diseases named in the same sentence as CRP in open-access papers (continued):
Sharing a sentence is not in itself a finding about the gene and the disease.
cardiovascular disease (continued). "Interest in serum GGT has been further amplified because of its association with other early predictors of cardiovascular disease, including high-sensitivity C-reactive protein, pulse wave velocity, and the Framingham risk score." (PMID 25452851, 2014). "In our study, the 56% decrease in CRP is clinically relevant because the value changed from a level considered “high risk” for cardiovascular disease at baseline (above 3.0 mg/L) to an “average risk” (1.0 to 3.0 mgL) after 1 year of the SARC intervention." (PMID 25136143, 2014). "It is well known that CRP is both a predictor and an independent risk factor for cardiovascular disease and is a predictor of cardiovascular mortality in patients with RA." (PMID 25337037, 2014). "For example, C-reactive protein levels are consistently associated with the risk of cardiovascular disease, but genetic studies negate the causality of the association." (PMID 24781247, 2014). "High sensitivity CRP is regarded as a reliable marker of inflammation and raised CRP levels have been associated with mortality in several studies of cardiovascular diseases." (PMID 24400123, 2014). "Of note, we observed that high CRP level was associated with substantially increased overall comorbidity and with previous cardiovascular disease mainly among men at time of Type 2 DM debut." (PMID 25163828, 2014). "The question remains, however, as to the value of CRP in assessing the risk of cardiovascular disease in males compared with females." (PMID 24944619, 2014). "Increased CRP levels have been recognized as an independent predictor of all-cause and cardiovascular mortality in cardiovascular disease and in the general population." (PMID 24885051, 2014). "Research and developments in this area have proved that CRP is instrumental in the initiation of several pathogenic pathways that can cause atherosclerosis, a precursor to cardiovascular disease." (PMID 25587427, 2014). "C-reactive protein (CRP) is a systemic inflammatory biomarker and a risk factor of cardiovascular disease." (PMID 25337797, 2014). "Lysophosphatidylcholines were negatively associated with body mass index, C-reactive protein and with less evidence of subclinical cardiovascular disease in additional 970 participants; a reverse pattern was observed for MG 18∶2." (PMID 25502724, 2014). "Much of the work in this area has been instigated by the association found between elevated basal CRP levels and increased risk for cardiovascular disease." (PMID 25359432, 2014). "Plasma CRP concentration is a clinically important marker of increased risk of cardiovascular disease, and CRP concentration in rabbits is increased by feeding a cholesterol-enriched diet for longer than 12 weeks." (PMID 24810608, 2014). "There is plenty evidence indicating the predictive value of CRP as a potent and strong independent risk marker for cardiovascular disease (CVD), and its morbidity and mortality." (PMID 24719806, 2014). "C-reactive protein (CRP) is a marker of inflammation and a risk predictor of cardiovascular disease." (PMID 23516433, 2013). "CRP is a predictor of subsequent cardiovascular disease, cardiovascular mortality, and all-cause mortality in the general population and in dialysis patients." (PMID 24007461, 2013). "The CRP variants, rs876538 and rs3093068, previously associated with other cardiovascular disease phenotypes, show suggestive association with PE in this American Indian population, further supporting a possible role for CRP in PE." (PMID 23940726, 2013). "Acute phase reactants produced in the liver, such as C-reactive protein (CRP) and fibrinogen, are elevated in obese adults and are implicated in the development of cardiovascular disease and T2D." (PMID 24454366, 2013). "C-reactive protein (CRP) levels are associated with cardiovascular disease and systemic inflammation." (PMID 23844046, 2013).
cardiovascular disease (continued). "High systemic concentrations of CRP have been also associated with the potential development of atherothrombotic events both in patients with known cardiovascular disease and in apparently healthy subjects." (PMID 24222887, 2013). "Recently, numerous epidemiological studies have shown that CRP is associated with an important risk factor used to assess cardiovascular disease, and has often been used as an indicator in health examinations." (PMID 23899933, 2013). "Increased levels of the inflammatory biomarker high-sensitivity C-reactive protein (hs-CRP) are associated with increased risk of cardiovascular disease." (PMID 24349092, 2013). "Chronic, low level increase in CRP has been associated with cardiovascular diseases, short sleep duration and sleep restriction." (PMID 24194869, 2013). "Four variables age (P = 0.008), serum IL-6 (P = 0.008), serum hs-CRP (P < 0.0001), and the -174G>C polymorphism (P = 0.029) were significantly associated with cardiovascular disease phenotype." (PMID 24363620, 2013). "The cohort also had a low cardiovascular disease risk factor profile with a mean systolic blood pressure of 119.5±35 mm Hg, total cholesterol 210.3±60.7 mg/dL, C-reactive protein levels 1.1 ± 1.3 mg/L and Framingham risk score 1.7±0.5." (PMID 23991206, 2013). "CRP is a strong predictor of cardiovascular disease which improves following weight loss and reduction of insulin sensitivity." (PMID 23986778, 2013). "Individuals with C-reactive protein (CRP) concentrations > 3 mg/L are at significantly elevated risk for cardiovascular disease while high-normal levels (2 ~ 3 mg/L) indicate low grade systemic inflammation." (PMID 23978069, 2013). "A previous study suggested that C-reactive protein levels require approximately 5 years to return to baseline after smoking cessation, even after controlling for other cardiovascular disease risk factors." (PMID 22496918, 2012). "Previous history of cardiovascular disease and higher hs-CRP levels were also found to be independent risk factors for all-cause and cardiovascular mortality." (PMID 23144974, 2012). "CRP is an inflammatory marker of cardiovascular disease; elevated levels are associated with increased risk of future coronary heart disease." (PMID 22533665, 2012). "The concentrations of most of these proteins were higher in users, including those that are established biomarkers of cardiovascular disease risk, such as CRP and angiotensinogen." (PMID 22984625, 2012). "Contribution of PTX3 and C-reactive protein level or the combination of the two to the risk prediction of prevalent cardiovascular disease." (PMID 22319633, 2012). "Elevated serum high-sensitivity C-reactive protein (hs-CRP) and low serum 25-hydroxyvitamin D [25(OH)D] are associated with increased cardiovascular disease (CVD) risk." (PMID 23029606, 2012). "Persistently elevated CRP values in the course of RA increase the risk of death due to cardiovascular disease." (PMID 22933832, 2012). "In previous studies, blood concentrations of homocysteine, uric acid, CRP, blood pressure and blood lipids were associated with cardiovascular disease risk." (PMID 23095712, 2012). "Individuals with high CRP levels showed a 30% higher risk for all-cause and cardiovascular diseases-mortality compared to those with low CRP levels." (PMID 23091306, 2012). "Elevated CRP concentration in the blood is a well recognized risk factor for future cardiovascular disease, although some studies argue against a causative role for CRP." (PMID 21611116, 2011). "Low-grade systemic inflammation, mainly characterised by increased CRP, is associated with an increased risk of cardiovascular disease, and obese individuals have higher CRP levels than subjects of normal weight." (PMID 22254115, 2011). "The short chain pentraxin, C-reactive protein, has been offered as an early diagnostic marker for cardiovascular diseases." (PMID 21876831, 2011).
cardiovascular disease (continued). "In the general population, CRP levels above 3 mg/L are considered high risk for cardiovascular disease." (PMID 22073156, 2011). "C-reactive protein (CRP) is one of the acute phase proteins that increases during systemic inflammation and measuring CRP levels in the blood is useful as an indicator of cardiovascular disease risk." (PMID 21569436, 2011). "So far, only few studies have considered all such possibilities or had the ability to take into account cardiovascular disease, risk factors and genetic determinants of CRP as means of testing causality." (PMID 21915265, 2011). "The Combined effect of Cytomegalovirus (CMV) Serostatus and C-reactive Protein (CRP) Level on All-Cause/Cardiovascular Disease (CVD) -related Mortality in Subjects 25 Years of Age and Older in NHANES III." (PMID 21379581, 2011). "C-reactive protein (CRP) is positively associated with risk for cardiovascular disease and all-cause mortality." (PMID 21939559, 2011). "C-reactive protein (CRP), a biomarker of inflammation, has been associated with increased risk of developing cardiovascular disease." (PMID 20716378, 2010). "In recent years there has been great interest in the role of high sensitivity C-reactive protein (hs-CRP) as a stable plasma biomarker of low-grade, chronic, systemic inflammation in predicting risk for cardiovascular disease in adults." (PMID 19995398, 2010). "Serum samples stored for similar periods of time have shown significant associations of D-dimer, and CRP, with risk of cardiovascular disease, and with risk factors such as cigarette-smoking." (PMID 21103357, 2010). "CRP and PP are well-established risk factors for cardiovascular disease and are elevated among individuals with the conditions found to be prevalent in the Puerto Rican population." (PMID 20123638, 2010). "The prototypic long pentraxin PTX3 is also associated with cardiovascular disease independently of CRP." (PMID 20920344, 2010). "Elevated levels of serum CRP is one of the most important indicators of inflammation and it is a significant risk factor for cardiovascular disease (CVD)." (PMID 20944519, 2010). "Elevated baseline C-reactive protein (CRP) levels are associated with increased risk for developing cardiovascular disease." (PMID 19426506, 2009). "The Women’s Health Study showed that, in middle-aged women, CRP and fibrinogen explained little of the socioeconomic differences in cardiovascular disease in addition to the effect of traditional coronary risk factors." (PMID 20015318, 2009). "Inflammatory markers that have been implicated as risk factors for cardiovascular disease include C-reactive protein, interleukins, serum amyloid A, vascular and cellular adhesion molecules, and white blood cell count." (PMID 20339564, 2009). "To date, C-reactive protein (CRP), a sensitive indicator of systemic inflammation, is the best biomarker for the excess cardiovascular disease associated with RA." (PMID 19606218, 2009). "For example, patients with COPD have increased levels of systemic inflammation, with CRP levels being associated with increased mortality, possibly through cardiovascular disease." (PMID 19480658, 2009). "Elevated serum CRP is a risk factor for cardiovascular diseases and predicts future cardiovascular events and even mortality in apparently healthy people." (PMID 19240794, 2009). "Epidemiological studies have shown associations between increased concentrations of SAA and CRP in plasma, and increased risk of cardiovascular diseases and cancer." (PMID 19374780, 2009). "Chronic infections which are known to cause a rise in circulating CRP levels also lead to a higher risk for cardiovascular disease." (PMID 20407653, 2009). "Among those reported to be independent predictors of cardiovascular disease risk are C-reactive protein (CRP), soluble intercellular adhesion molecule-1 (sICAM-1), and leptin." (PMID 18775082, 2008).
cardiovascular disease (continued). "Several studies have demonstrated plasma levelsof CRP positively associated with risk of cardiovascular disease and clinicalevents." (PMID 19107216, 2008). "Serum concentrations of proteins associated with risk for cardiovascular disease, including C-reactive protein (CRP), soluble intercellular adhesion molecule-1 (sICAM-1), and leptin, were also measured." (PMID 18775082, 2008). "Slight elevations in serum CRP concentration, such as those observed in the present study, are thought to be a risk factor for cardiovascular disease and have been associated with particulate air pollution." (PMID 17827864, 2007). "High sensitivity serum C-reactive protein (hs-CRP) has come into clinical use as a marker of risk for cardiovascular disease (CVD)." (PMID 19690638, 2007). "Instead of CRP we evaluated leukocyte number which was similarly associated with mortality, suggesting a link to systemic inflammation, as in cardiovascular diseases." (PMID 18086309, 2007). "Among the upregulated proteins, C-reactive protein (CRP) showed the greatest increase in obese individuals (fold change = 2.23), consistent with its established role as an inflammatory biomarker associated with metabolic dysfunction and cardiovascular disease." (PMID 40981199, 2025). "RDW has been shown to be significantly associated with CRP and cardiovascular disease mortality." (PMID 40893933, 2025). "Consequently, it is associated with elevated levels of CRP, a marker of inflammation and cardiovascular disease." (PMID 40329709, 2025). "Furthermore, the authors clearly suggest caution with the evaluation of CRP as it is generally associated with cardiovascular diseases, which can also lead to worse OS, along with the HCC presence." (PMID 40948746, 2025). "Additionally, high-sensitivity C-reactive protein (hs-CRP) is a well-known predictor of cardiovascular disease and is closely associated with coronary artery disease caused by stress and other diseases." (PMID 40095921, 2025). "More specifically, C‐reactive protein (CRP, mmol/L) has been identified as a common marker of systemic inflammation that underlies several health risks and outcomes and has been linked with an overall increased risk of cardiovascular diseases." (PMID 40285470, 2025). "Elevated levels of CRP may potentially elucidate the heightened susceptibility of some patients with PCOS to the beginning of cardiovascular disease (CVD) at an earlier age." (PMID 39036884, 2024). "CRP has been widely associated with cardiovascular diseases." (PMID 39138803, 2024). "C-reactive protein, a marker of the acute-phase inflammatory response, has been widely used to measure low-level inflammation in psychiatric disorders and has provided valuable information in cardiovascular disease diagnosis and risk prediction." (PMID 38596631, 2024). "An elevation in the CRP levels is also a strong independent predictor of cardiovascular disease in asymptomatic individuals and they have been linked to prognosis in patients with atherosclerotic disease, suggesting that they play an active role in the pathophysiology of CVD." (PMID 39453923, 2024). "It has demonstrated potential in reducing cardiovascular disease risk by lowering levels of pro-inflammatory markers such as C-reactive protein (CRP) and cytokines IL-6 and IL-1β, with its action mediated through the inhibition of C/EBP-δ and NF-κB signaling pathways." (PMID 39125589, 2024). "In addition, many previous studies have indicated that CRP is a marker of subclinical cardiovascular events in RA patients, and an increase in CRP levels is associated with an increased risk of cardiovascular disorders in this population." (PMID 39160453, 2024). "For instance, CRP has been found to be among the most prevailingly known inflammatory biomarkers, exhibiting consistency in large prospective research as a risk factor of similar significance as traditional risk factors for cardiovascular diseases." (PMID 39107719, 2024).
cardiovascular disease (continued). "This anti-inflammatory effect may be related to metformin’s impact on certain inflammatory mediators, such as C-reactive protein and interleukin-6, which are known risk factors for cardiovascular diseases." (PMID 38553738, 2024). "A few studies demonstrated that elevated CRP levels above 3 mg/L could predict the occurrence of cardiovascular events and significantly increase the risk of all-cause and cardiovascular disease-related death." (PMID 38074681, 2023). "Some studies have found that biomarkers such as serum B-type natriuretic peptide precursor (BNP),calcitoninogen, cardiac troponin (cTn), highly sensitive C-reactive protein (Hs-CRP), D-dimer, and Interleukin-6 (IL-6) levelsare associated with the occurrence of cardiovascular disease." (PMID 39077519, 2023). "PCOS patients with elevated C-reactive protein levels may be at a greater risk for developing T2D and cardiovascular disease." (PMID 36677054, 2023). "It was reported in a previous study that examined the relationship between inflammatory factors and cardiovascular diseases that WBC, CRP, and monocyte levels might be risk determinants for cardiovascular diseases." (PMID 36836510, 2023). "Cohort studies have shown that elevated CRP is associated with mortality and cardiovascular disease (CVD) events for patients with various CVD locations like coronary artery disease, cerebrovascular disease, peripheral artery disease, and abdominal aortic aneurysm." (PMID 38293298, 2023). "An increase in serum CRP is a risk factor for cardiovascular disease." (PMID 38077410, 2023). "Increased levels of CRP are a risk factor for cardiovascular disease." (PMID 37372026, 2023). "CRP is primarily under regulation of IL-6 and is widely associated with cardiovascular diseases, since more than 20 large prospective studies suggest that hsCRP could be a predictor of future cardiovascular events." (PMID 37371494, 2023). "Interestingly, in the absence of sample collection control, the number of naturally menstruating elite athletes that were considered to be at low risk of cardiovascular disease (CRP <1 mg L−1) was double that of the number of OCP users." (PMID 37487629, 2023). "Taken together, the current research evidence suggests that high levels of fibrinogen, interleukin-6, C-reactive protein and galectin-3 are risk factors for cardiovascular disease and can be used as biomarkers to predict the development of cardiovascular disease to some extent." (PMID 37485268, 2023). "In summary, patients with hip fracture presenting with a higher baseline CRP level may be at higher risk of developing cardiovascular diseases, which leads to a higher mortality rate compared with that of patients with a lower baseline CRP level." (PMID 36894998, 2023). "The results of a previous randomized double-blinded controlled trial revealed that supplementation with adequate multivitamins and minerals can reduce the blood pressure and serum C-reactive protein levels in obese women with an increased risk of cardiovascular disease." (PMID 35360520, 2022). "CRP represents an independently risk factor for various cardiovascular diseases." (PMID 35574553, 2022). "We assessed whether circulating levels of glycoprotein acetyls (GlycA) were better able to predict the development of adverse cardiovascular disease risk profiles compared with the more commonly used biomarker high‐sensitivity CRP (C‐reactive protein)." (PMID 35156387, 2022). "Moreover, elevated serum levels of TNF-α, IL-6 and CRP have been shown to increase the risk of cardiovascular diseases." (PMID 36434695, 2022). "In risk stratification of cardiovascular disease, the groups of low risk (< 1.0 mg/L), average risk (1.0 to 3.0 mg/L), and high risk (> 3.0 mg/L) approximately correspond to tertiles of CRP in the general adult population, which were derived from more than 40,000 persons in more than 15 populations." (PMID 36117174, 2022).